NANOS3 (nanos C2HC-type zinc finger 3)
Diseases named in the same sentence as NANOS3 in open-access papers:
NANOS3 is named in the same sentence as 17 diseases in open-access papers, as found by Europe PMC text mining. Sharing a sentence is not in itself a finding about the gene and the disease. The quoted sentences say what the papers report.
Infertility (8 papers, 2014 to 2025). "The importance of NANOS1 and NANOS3 for human fertility was demonstrated by identification of mutations in those genes in infertile patients." (PMID 35743036, 2022). "Although mutations in NANOS1 and NANOS3 are associated with pathology of germ cells resulting in infertility, the underlying molecular mechanism of the function of NANOS proteins in the context of human germ cell development and biology remains elusive." (PMID 35743036, 2022). "On the other hand, two out of four NANOS3 mutations were detected to be linked to premature ovarian insufficiency (POI) in infertile women." (PMID 32344590, 2020). "Apoptosis of PGCs is suppressed by NANOS3, and knockout of the murine gene causes infertility in both sexes." (PMID 32344590, 2020). "In mice, loss of Nanos3 results in infertility due to apoptosis of migrating PGCs during fetal life, resulting in atrophic gonads where germ cells are absent." (PMID 25054146, 2014). "Our study provides the first transcriptomic characterization upon induced expression of NANOS1 and NANOS3 in a human germ cell model with an emphasis on mRNAs related to infertility and cancer, many of which carry out functions related to the cell cycle." (PMID 35743036, 2022). "On the other hand, NANOS3 and FOXM1 expression is enriched in human germ cells and a significant fraction of NANOS3 downregulated infertility (19/52) and cancer-germ cell genes (28/53) are also FOXM1 transcriptional targets (iRegulon)." (PMID 35743036, 2022). "Although no mutations related to male infertility have been found in this gene so far, a knockout of murine Nanos3 resulted in infertility of both sexes, which is in accordance with similar murine and human expression patterns of those orthologues." (PMID 35743036, 2022). "NANOS3-null mice show infertility resulting from apoptosis of migrating PGCs during the fetal stage, resulting in gonads lacking germ cells." (PMID 27117862, 2016). "Nanos3 belongs to the Nanos gene family, and is expressed in the primordial germ cells of mammals; Nanos3 knockout mice have smaller gonads and infertility in both male and female mice." (PMID 26030766, 2015). "While disruption of NANOS2 and NANOS3 in mice causes infertility, NANOS1, although expressed in germ cells, does not seem to play a significant role in reproduction or other processes in mouse physiology." (PMID 41107697, 2025). "Therefore, screening for NANOS3 gene variants was conducted on a group of 214 patients from the Polish cohort diagnosed with non-obstructive infertility, including azoospermia or oligospermia." (PMID 41107697, 2025). "NANOS3 gene mutations were found in a group of infertile men, but no causation was detected." (PMID 32344590, 2020). "Since we have identified cell cycle related functions as a common theme for both infertility and cancer-germ cell genes downregulated by NANOS1 and NANOS3, we sought to interrogate the functional relationship between them." (PMID 35743036, 2022). "We identified 26 and 52 infertility genes downregulated as well as 28 and 53 cancer-germ cell genes downregulated for NANOS1 and NANOS3, respectively." (PMID 35743036, 2022). "Interestingly, many of these genes are involved in the cell cycle, i.e., 10/26 (34%) NANOS1 and 15/52 (27%) NANOS3 infertility genes as well as 9/28 (32%) NANOS1 and 19/53 (36%) NANOS3 cancer-germ cell genes are cell cycle related." (PMID 35743036, 2022). "As Nanos3 expression in mice embryos is detected as early as E7.5 during PGC specification, the infertility observed in both male and female Trim71 cKO mice may reflect a function of TRIM71 in an early stage of germ cell development." (PMID 34055789, 2021). "Unlike Nanos2 and Nanos3 knockout resulting in mice infertility, Nanos1 knockout mice are viable and fertile, indicating that the NANOS1 protein is dispensable for mouse development and fertility." (PMID 32344590, 2020).
Infertility (continued). "Finally, many of these infertility and cancer-germ cell genes are present together in cell cycle related clusters downregulated by NANOS1 and NANOS3, suggesting a potential role of NANOS-mediated regulation of cell cycle process for proper human germ cell development and fertility." (PMID 35743036, 2022).
Premature ovarian insufficiency (4 papers, 2021 to 2025). Amenorrhea due to loss of ovarian function before the age of 40. "Specifically, the NANOS3 homozygous gene variant p.E120K, linked to premature ovarian insufficiency, was identified in two Brazilian sisters and produced a stable NANOS3 protein." (PMID 41107697, 2025). "A missense variant of NANOS3 was identified in a study of Chinese women with primary ovarian insufficiency, and the level of NANOS3 protein was shown to correlate with the number of primordial germ cells." (PMID 34193292, 2021).
glioblastoma (3 papers, 2020 to 2022). The most malignant astrocytic tumor (WHO grade IV). "In a study, the CRISPR-Cas9 knockdown of NANOS3 in glioblastoma cell lines resulted in reduced proliferation, migration, and invasiveness, suggesting a role for NANOS3 in this disease." (PMID 36012673, 2022). "Further research on how NANOS3 overexpression contributes to the pathogenesis of glioblastoma would lead to a better understanding of this disease." (PMID 36012673, 2022). "Another study showed the overexpression of NANOS3 in glioblastoma cell lines and tissues." (PMID 36012673, 2022). "Moreover, xenografting NANOS3 knockdown cells obtained from glioblastoma cell lines into mice in comparison to control xenografts significantly reduced the tumor’s growth." (PMID 36012673, 2022). "We found that Nanos3 was strongly expressed in both glioblastoma cell lines and tissues." (PMID 32508533, 2020). "Therefore, Nanos3 knockdown was found to suppress the oncogenicity of glioblastoma by inhibiting the cancer-germline characteristics and tumor cells growth, and increasing the glioma cells differentiation." (PMID 32508533, 2020). "In addition, NANOS3 expression normally restricted to germ cells has been detected in various human cancers and reported to promote proliferation and migration of human glioblastoma cells." (PMID 34205983, 2021). "RT-PCR showed that Nanos3 was generally overexpressed in GBM cells and the mouse glioblastoma tissues (case 1–4) compared with its expression in normal human astrocytes (NHA) cells and the normal mouse brain." (PMID 32508533, 2020). "Moreover, high-level ectopic expression of Nanos3 is an independent marker of overall survival and may therefore be essential for the progression of glioblastoma." (PMID 32508533, 2020). "Western blot data confirmed that Nanos3 was overexpressed in all GBM cell lines and mouse glioblastoma tissues (glioblastoma 1–5) compared with NHA cells and normal mouse brains." (PMID 32508533, 2020). "Thus, Nanos3 is expressed at high levels in glioblastoma cells and glioblastoma tissues." (PMID 32508533, 2020). "Immunofluorescence indicated that Nanos3 was expressed in the glioblastoma cells, especially in A172 cells, but not expressed in the NHA cells." (PMID 32508533, 2020).
glioma (2 papers, 2020 to 2022). A benign or malignant brain and spinal cord tumor that arises from glial cells (astrocytes, oligodendrocytes, ependymal cells). "Consistent with this, high expression of the genes associated with PGC fate determination usually did not lead to poor outcomes of gliomas, such as KIT, DND1, NANOS3 and DDX4." (PMID 36435765, 2022).
primary ovarian failure (2 papers, 2016 to 2021). Absent or premature cessation of ovarian function due to a pathologic process originating within the ovaries. "The aim of this study was to search for mutations in NANOS3, a gene that was recently related to the etiology of primary ovarian failure, in a group of Brazilian women." (PMID 28076512, 2016). "We screened for NANOS3 DNA variants in 30 consecutive women who were previously diagnosed with primary ovarian failure, of unknown etiology and compared the results with those from 185 women with normal fertility." (PMID 28076512, 2016).
teratoma (2 papers, 2013 to 2020). A non-seminomatous germ cell tumor characterized by the presence of various tissues which correspond to the different germinal layers (endoderm, mesoderm, and ectoderm). "However, the following are unclear: (a) whether DND1 works with NANOS2 or NANOS3 to regulate teratoma incidence, and (b) whether Ter simply causes Dnd1 loss or produces a short mutant DND1 protein." (PMID 32339196, 2020). "We further demonstrate that mice with a heterozygous deletion of the TFAP2C target gene Nanos3 are also prone to develop teratomas." (PMID 23967156, 2013). "In addition to these genetic interactions, given that both NANOS2 and NANOS3 associate with DND1, it is highly plausible that both DND1-NANOS2 and DND1-NANOS3 complexes regulate teratoma incidence in male embryonic germ cells." (PMID 32339196, 2020). "Interestingly, from the fourth generation in 129S2/Sv 45% of Nanos3 heterozygous males showed teratoma formation (n = 20), with 5% showing bilateral tumors, whereas control animals (n = 17) remained tumor-free." (PMID 23967156, 2013).
testis cancer (2 papers, 2022). "Moreover, FOXM1 and NANOS3 expressions are negatively correlated in human testis cancer." (PMID 36012673, 2022). "Taken together, we demonstrate the interplay between NANOS3, PUM1, and FOXM1 in regulating G2/M phase genes and disruption of this interplay in testicular cancer." (PMID 35743036, 2022). "This analysis showed a much wider expression pattern for PUM1, NANOS3, FOXM1, and target cell cycle genes in testis cancer compared to healthy testis samples including altered NANOS3-FOXM1 and PUM1-FOXM1 correlations." (PMID 35743036, 2022). "To address this, we analyzed the correlation between NANOS1 and NANOS3 with its upstream transcriptional program in human primordial germ cells including transcription factors PRDM1, SOX17, TFAP2C, and PRDM14 expression in testis cancer samples." (PMID 36012673, 2022).
germ cell tumor (1 paper, 2013). A benign or malignant, gonadal or extragonadal neoplasm that originates from germ cells. "Interestingly, the authors found Nanos3 haploinsufficiency to modify the susceptibility of Dmrt1 deficient male mice by elevating the tumor incidence, clearly demonstrating a role of Nanos3 in germ cell tumor development." (PMID 23967156, 2013). "In line with this, we demonstrate that haploinsufficiency of Tfap2c or its target gene Nanos3 lead to high rate of GCC in 129S2/Sv mice, resembling human pediatric germ cell tumors." (PMID 23967156, 2013).
Kawasaki disease (1 paper, 2022). A rare inflammatory disease characterized by an acute febrile, systemic, self-limiting, medium-vessel vasculitis primarily affecting children. "SNP rs8108402 C/T located in the miR-181c/d promoter and Nanos3 intronic region is associated with susceptibility to Kawasaki disease but not with the development of coronary artery lesions or IVIG unresponsiveness in Chinese children." (PMID 36016885, 2022).
Primary amenorrhea (1 paper, 2014). "We have identified a nonsynonymous homozygous NANOS3 mutation in two sisters with primary amenorrhea." (PMID 25054146, 2014). "A homozygous p.Glu120Lys mutation in NANOS3 was identified in two sisters with primary amenorrhea." (PMID 25054146, 2014). "It is remarkable that our two patients with homozygous NANOS3 mutation have presented with primary amenorrhea, perhaps indicating more severely PGC-depleted ovaries, while their heterozygous mother had difficulty to conceive, which could represent a manifestation of insufficient PGC pool size." (PMID 25054146, 2014).
systemic lupus erythematosus (1 paper, 2022). An autoimmune multi-organ disease typically associated with vasculopathy and autoantibody production. "The miR-181c/d gene locus rs8108402 C/T is located in the promoter region of miR-181c and miR-181d genes and the intron of the Nanos3 gene and has been previously found to be associated with susceptibility to systemic lupus erythematosus." (PMID 36016885, 2022).
testicular teratoma (1 paper, 2020). "In the case of crossing with Nanos3 mutant mice, the ratio of affected male mice increased from 4.4% in wild-type male mice to 24.2% in Nanos3+/Cre male mice, indicating that Nanos3 is one of the genes responsible for testicular teratomas, as previously reported." (PMID 32339196, 2020). "We have previously shown that DND1 functions with NANOS2 or NANOS3 in both male embryonic germ cells and adult spermatogonia, which raises the question of whether DND1 also acts as a partner of NANOS family proteins to regulate the incidence of testicular teratoma." (PMID 32339196, 2020). "We have previously shown that both NANOS2 and NANOS3 interact with DND1 and that these complexes are essential for germ cell development, leading us to speculate that both NANOS2 and NANOS3 play a vital role with DND1 even in the regulation of testicular teratoma incidence." (PMID 32339196, 2020).
cancer (5 papers, 2019 to 2022). A tumor composed of atypical neoplastic, often pleomorphic cells that invade other tissues. "Collectively, these studies show that the overexpression of NANOS3 in cancers is highly linked with an increase in tumor invasiveness, metastasis, and tumor growth." (PMID 36012673, 2022). "Upregulation of NANOS1 and NANOS3 facilitates the oncogenic growth of p-Rb-deficient cells, suggesting that Nanos has a dynamic role in cancer cell proliferation." (PMID 32508533, 2020). "Aberrant expression of Nanos3 has been functionally associated with various cancers." (PMID 32508533, 2020). "To this end we utilized the publicly available transcriptomic expression datasets from healthy and cancer testis samples and compared the correlation between NANOS3, PUM1, FOXM1, and the model cell cycle targets." (PMID 35743036, 2022). "Taken together, these studies demonstrate a potential mechanism of TFAP2C-mediated overexpression of NANOS3 in cancer." (PMID 36012673, 2022). "This suggests that the overexpression of NANOS3 contributes to the invasiveness of this type of cancer." (PMID 36012673, 2022). "These mice, in combination with different conditional and doxycycline-inducible Cre lines, allow the study of the role of ectopic Nanos3 expression in several cancer types." (PMID 31208373, 2019). "We chose this human cDNA because this transcript has been annotated in the curated human consensus coding sequence set (CCDS), and because of the reported relevance of ectopic Nanos3 expression in human cancers." (PMID 31208373, 2019). "It was shown that NANOS3 is overexpressed and is a marker of this type of cancer." (PMID 36012673, 2022). "Importantly, many of NANOS1 and NANOS3 target mRNAs represent genes previously identified as important factors for fertility as well as cancer-germ cell related genes." (PMID 35743036, 2022). "Hence, other tumor models using the Nanos3LSL alleles in combination with activated oncogenes and/or inactivated tumor suppressor genes may increase our knowledge of the in vivo roles of Nanos3 in various cancers." (PMID 31208373, 2019). "Moreover, in contrast to NANOS1, NANOS3 is not expressed in normal tissues except in testis and brain tissues, suggesting that it could be used as a marker for a broad range of cancers and, thus, is an attractive gene for diagnostic purposes in the future." (PMID 36012673, 2022). "We found that knockdown of Nanos3 significantly reduced GBM cell proliferation, tumorigenicity, and the characteristics of cancer-germline cells." (PMID 32508533, 2020). "Similarly to NANOS3 overexpression in cancer, TFAP2C overexpression was also reported in various cancer types." (PMID 36012673, 2022). "It is worth noting that Nanos3 is strongly expressed in adult germ cells but not in adult somatic tissues, except the brain; however, Nanos3 is ectopically expressed in many human cancers." (PMID 32508533, 2020).
tumor (5 papers, 2013 to 2022). "Therefore, it is interesting that tumor-associated stromal cells were eGFP-positive, and therefore most likely Nanos3-positive, in the case of tumors derived from alveolar tissue, whereas this could not be detected in tumors derived from bronchiolar tissue." (PMID 31208373, 2019). "The results of our initial experiments using this mouse model in the context of lung cancer support the idea that NANOS3 can be considered a tumor promoting gene." (PMID 31208373, 2019). "Interestingly, the potential role of Nanos3 in PGCs migration is in accordance with research, showing its implication in tumor invasiveness and metastasis." (PMID 36012673, 2022). "The observation that Nanos3 gene exerts oncogenic functions may explain the origin of the tumor cells." (PMID 32508533, 2020). "In line with this, we wondered whether Nanos3 overexpression affects tumor progression in vivo." (PMID 31208373, 2019). "Therefore, Nanos3 gene could represent ideal candidates, since it belongs to a unique group of CG genes that primarily contribute to some key process of tumor development, including unlimited proliferation, metastasis, adaption to cellular energetics constraints, and resistance to apoptosis." (PMID 32508533, 2020). "For the enhancer in chromosome 19, the target genes are TRMT1, TNPO2, NFIX, DNASE2, PRDX2, NANOS3, and LYL1, which was detected in 22 unique tumor samples." (PMID 29207666, 2017). "However, NANOS3 was found to be expressed in the nucleus and/or cytoplasm of human NSCLC tumor cells independently of their histological subtype." (PMID 31208373, 2019).
NANOS3 also shares sentences with these, for which no sentence is quoted: amenorrhea (1 paper); Azoospermia (1); lung carcinoma (1).